OR2W3 (olfactory receptor family 2 subfamily W member 3)
Description:
Odorant receptor.
Synonyms: OR2W3P; OR2W8P; OST718
Tractability: Antibody: its Gene Ontology location is reachable by antibodies, with high confidence; UniProt places it where antibodies can reach, with medium confidence; UniProt predicts a signal peptide or a membrane-spanning region.
Gene: Protein-coding gene on chromosome 1 (247,895,587 to 247,896,531, forward strand). Ensembl gene ENSG00000238243.
Subcellular location: Cell membrane
Pathways (Reactome):
Sensory Perception: Expression and translocation of olfactory receptors; Olfactory Signaling Pathway
Gene Ontology:
Molecular function: olfactory receptor activity; G protein-coupled receptor activity
Biological process: detection of chemical stimulus involved in sensory perception of smell; G protein-coupled receptor signaling pathway
Cellular component: plasma membrane; membrane
Genetic constraint (gnomAD): Loss-of-function variants: 0 observed, 0.36 expected, observed/expected ratio (o/e) 0, 90% interval 0 to 1.86. That is too few expected variants to judge how well the gene tolerates losing a copy. Missense variants: 448 observed, 415.62 expected, observed/expected ratio (o/e) 1.08, 90% interval 1 to 1.17. Synonymous variants: 196 observed, 176.43 expected, observed/expected ratio (o/e) 1.11, 90% interval 0.99 to 1.25.
Homologues: Orthologues: macaque OR2W3 (96% identical), dog OR2W3 (88% identical), mouse Or2w3 (84% identical), mouse Or2w3b (83% identical). Paralogues in human: OR2W1 (59% identical), OR2B6 (58% identical), OR2G2 (57% identical), OR2G3 (56% identical), OR2J2 (56% identical), OR2H2 (56% identical), OR2C1 (56% identical), OR2J1 (56% identical), OR2J3 (56% identical), OR2B2 (55% identical), OR2H1 (55% identical), OR2C3 (55% identical), and 80 more.
Diseases named in the same sentence as OR2W3 in open-access papers:
OR2W3 is named in the same sentence as 9 diseases in open-access papers, as found by Europe PMC text mining. Sharing a sentence is not in itself a finding about the gene and the disease. The quoted sentences say what the papers report.
breast carcinoma (3 papers, 2019 to 2022). "Our results also discovered that significant OR2W3 overexpression occurs in the patient sub-populations with elevated levels of breast cancer invasion-related genes and basal-like subtypes that are classified as TNBC." (PMID 31551495, 2019). "In addition, OR2W3 upregulation was associated with reduced survival in invasive breast carcinoma, suggesting that it may be a potential breast cancer invasion marker, with possible roles in breast cancer progression and metastasis requiring further investigation." (PMID 33963380, 2021). "Similarly, OR2W3 upregulation level was nearly 10-fold greater in invasive breast carcinoma patients (sub-population III) compared to human breast cancer cell lines (group III)." (PMID 31551495, 2019). "OR2W3, which belongs to the ORS gene family, has been revealed to be related to the progression of breast cancer." (PMID 35847579, 2022).
follicular thyroid cancer (2 papers, 2021 to 2025). "In vitro characterization confirmed that ligand OR2H2 and OR2W3 interaction has a functional impact on cancer biology, increasing the invasive potential of follicular thyroid cancer cells." (PMID 34385931, 2021). "Activation of OR2W3 enhances cell invasion in the follicular thyroid cancer (FTC133) cell line without affecting migration." (PMID 40128298, 2025).
aortic aneurysm (1 paper, 2024). A ruptured aneurysm located in the wall of the proximal portion of the descending aorta proceeding from the arch of the aorta. "In addition, evaluating the function of other, similar receptors found on the platelet surface (OR2W3, OR2B6) in the context of aortic aneurysm and vascular wall inflammation may provide additional context regarding platelet activation in these cases." (PMID 39768700, 2024).
thyroid cancer (1 paper, 2021). "In sum, we demonstrate that ORs such as OR2H2 and OR2W3 are not only expressed in healthy human thyroid tissue but also human thyroid cancer cells and respond to their ligands via a combination of cAMP and IP3 dependent signaling." (PMID 34385931, 2021).
tumor (2 papers, 2020 to 2025). "The expression of OR2W3 can promote dysplasia and local aggressive growth of tumor cells." (PMID 32340320, 2020). "Analysis of GSE99671 revealed significantly higher expression levels of KLK2, NRXN1, HES5, OR2W3, and HS3ST4 in normal samples compared to tumor samples." (PMID 40128298, 2025).
OR2W3 also shares sentences with these, for which no sentence is quoted: invasive breast carcinoma (2 papers); cancer (1); glaucoma (1); male infertility (1).